STAT4 (signal transducer and activator of transcription 4)
Diseases named in the same sentence as STAT4 in open-access papers (continued):
Sharing a sentence is not in itself a finding about the gene and the disease.
atherosclerosis (10 papers, 2017 to 2026). A disease characterized by the build-up of fatty material and calcium deposition in the arterial wall resulting in partial or complete occlusion of the arterial lumen. "Generation of both myeloid-specific and neutrophil-specific STAT4-deficient mice allowed us to pinpoint to what degree STAT4 contributes to atherosclerosis within the entire myeloid compartment and individually from neutrophils." (PMID 37396582, 2023). "Next, we sought to determine how STAT4 deficiency in neutrophils affects their expression profile upon atherosclerosis development." (PMID 37396582, 2023). "Together, these data demonstrate that STAT4 deficiency results in the reduction of several key aspects of neutrophil activation that impact the progression of atherosclerosis and promote plaque instability." (PMID 37396582, 2023). "While the role of IL-12 in AD pathology and atherosclerosis is relatively established, the role of Stat4 in neuroinflammation and associated AD structural or functional pathology under pro-atherogenic conditions has not been investigated." (PMID 37783748, 2023). "Overall, our data reveal an important role for myeloid-driven STAT4 expression in the pathogenesis of cognitive decline associated with atherosclerosis, mediated through impaired efferocytosis and enhanced leukocyte activation, leading to increased brain neuroinflammation." (PMID 41929047, 2026). "Here, we demonstrate that STAT4 deficiency in neutrophils results in reduced expression of chemokine receptors while exhibiting reduced capacity of activated neutrophils to migrate to sites of atherosclerosis." (PMID 37396582, 2023). "As macrophages and neutrophils play key roles in both processes, we asked whether STAT4 deficiency in these cells during advanced atherosclerosis would improve either of these destabilizing features within the aortic root." (PMID 37396582, 2023). "We have previously established a role for STAT4 in atherosclerosis in mice, whereby global STAT4 deficiency improves atherosclerotic burden primarily associated with altered T follicular helper (Tfh) differentiation and increased presence of protective CD8+ T regulatory cells." (PMID 37396582, 2023). "To assess the role of STAT4 in neutrophil biology during advanced atherosclerosis, we first sought to determine whether STAT4-deficiency affects circulating neutrophil abundance." (PMID 37396582, 2023). "Recent findings from a murine model of advanced atherosclerosis indicate that the pro-atherosclerotic activity of neutrophils depends on signaling by Signal transducer and activator of transcription 4 (STAT4)." (PMID 39161593, 2024). "Since STAT4 functions as a transcription factor, it was important to address to what degree Stat4 influences the neutrophil gene expression profile during atherosclerosis." (PMID 37396582, 2023). "To further our understanding of how STAT4 contributes to neutrophil biology during advanced atherosclerosis at the functional level, we analyzed several aspects of neutrophil activation." (PMID 37396582, 2023). "The data presented here support a role for the inflammatory transcription factor Stat4 in neuroinflammatory synaptotoxicity and cognitive impairments associated with HFD-C diets, atherosclerosis, and metabolic dysfunction." (PMID 37783748, 2023). "Our work indicates a pro-atherogenic role for STAT4-dependent neutrophil activation and how it contributes to multiple factors of plaque instability during advanced atherosclerosis in mice." (PMID 37396582, 2023). "The reduced frequency of neutrophil-platelet aggregates in Stat4ΔLysMLdlr−/− mice further supports STAT4 as a critical driver of neutrophil activation during advanced atherosclerosis and the promotion of plaque destabilization." (PMID 37396582, 2023). "Altogether, these findings demonstrate STAT4 as a novel regulator of neutrophil homing to sites of atherosclerosis." (PMID 37396582, 2023).
atherosclerosis (continued). "Overall, these data emphasize the milieu of inflammatory genes upregulated in neutrophils during atherosclerosis and highlight STAT4 as a novel regulator of several key proatherogenic genes in neutrophils." (PMID 37396582, 2023). "To examine the role of STAT4 in myeloid cells during advanced atherosclerosis, we successfully generated myeloid-specific (Stat4ΔLysMLdlr−/−), neutrophil-specific (Stat4ΔS100A8Ldlr−/−), and Stat4-sufficient floxed control (Stat4fl/flLdlr−/−) mice." (PMID 37396582, 2023). "Higher prevalence of the STAT4 risk allele has been associated with cardiovascular risk in SLE patients and atherosclerosis animal models." (PMID 34099646, 2021). "As a transcription factor, STAT4 has appeared to be a major regulator of T-cell activation, macrophage inflammatory phenotype, insulin resistance and atherosclerosis." (PMID 30044774, 2018). "STAT4 has emerged as an important transcription factor regulating T-cell activation, macrophage inflammatory phenotype, insulin resistance and atherosclerosis." (PMID 28107529, 2017). "Here, we examine whether STAT4 functions as a common mediator of neuroinflammation in atherosclerosis." (PMID 41929047, 2026). "Atherosclerosis alters brain immune composition, characterized by increased numbers of CD45+ leukocytes, activated microglia, and activated T and B cells, whereas STAT4 deficiency attenuates these effects." (PMID 41929047, 2026). "However, our demonstrated correlation of reduced Cybb expression with reduced mitochondrial superoxide production in neutrophils revealed STAT4 as a novel contributor to neutrophil oxidative stress during atherosclerosis." (PMID 37396582, 2023). "The cytokine interleukin-12 activates signal transducer and activator of transcription 4 (Stat4), and consumption of a high-fat, high-cholesterol diet (HFD-C) and Stat4 activity are associated with inflammation, atherosclerosis, and a diabetic metabolic phenotype." (PMID 37783748, 2023). "We therefore hypothesized that STAT4 in neutrophils would participate in atherosclerosis development and plaque instability." (PMID 37396582, 2023). "STAT4 absence could reduce the development of atherosclerosis by affecting MΦ activation and CCL2-induced MΦ migration." (PMID 36816804, 2023). "Therefore, we investigated a contributory role of STAT4 in neutrophils during advanced atherosclerosis." (PMID 37396582, 2023). "Our data clearly demonstrate STAT4 as a novel regulator of neutrophil inflammatory mechanisms during advanced atherosclerosis, which could offer new therapeutic avenues for the prevention of atherosclerotic plaque destabilization." (PMID 37396582, 2023). "Together, these findings suggest that myeloid STAT4 plays a role in neutrophil differentiation at basal conditions and upon hyperlipidemia-induced myelopoiesis that contributes to the circulating pool of neutrophils during advanced atherosclerosis." (PMID 37396582, 2023). "As IL-12 is involved in inflammatory processes in atherosclerosis and neuroinflammation, and Stat4 is an important component of the IL-12-dependent response, we sought to test whether Stat4 is expressed in the brain of HFD-C fed Stat4fl/flLdlr−/− atherosclerotic mice." (PMID 37783748, 2023). "Next, the effects of KLF10 on Tregs-regulated macrophages in atherosclerosis and the effects of MSCs, IL-12p35, HCW9302, MicroRNA-33, STAT4, and HHcy on Tregs and macrophages in atherosclerosis are explained." (PMID 39582868, 2024). "It turned out that STAT4 participated in atherogenesis via the support of pro-inflammatory activities of macrophages, regulation of the CD8+ Treg/T follicular helper cell axis, and modulation of the local immune response in the aortic wall under conditions of IR and atherosclerosis." (PMID 39582868, 2024).
nephritis (10 papers, 2008 to 2022). Inflammation of renal tissue. "In SLE patients there is an association between STAT4 genotype and a more severe phenotype, which includes nephritis and presence of anti-dsDNA autoantibodies." (PMID 22066971, 2011). "In particular, we have found that the STAT4 susceptibility polymorphism is associated with more severe disease manifestations, including nephritis and early disease onset." (PMID 18516230, 2008). "In summary, our study has identified multiple correlated subphenotypes that are strongly associated with the STAT4 gene, including nephritis, autoantibodies to double-stranded DNA, and early age at diagnosis." (PMID 18516230, 2008). "Of note, SLE patients having clinical signs of nephritis show a strong association with STAT4." (PMID 29467950, 2018). "Thus, there is an association between STAT4 genotype and risk for a more severe disease phenotype that includes nephritis and stroke." (PMID 22066971, 2011). "Moreover, the STAT4 risk allele is also associated with specific clinical manifestations including earlier age at diagnosis, presence of anti-dsDNA, ischemic cerebrovascular disease, nephritis, and severe renal insufficiency." (PMID 35493285, 2022). "For example, variants of signal transducer and activator of transcription 4 (STAT4) have been associated with a more severe disease phenotype, including ischemic stroke, nephritis and increased SDI scores." (PMID 35743441, 2022). "To determine if SLE-related genetic variants associate specifically with nephritis in SLE patients, we genotyped up to nine variants from the IRF5, STAT4 genes and the TRAF1-C5 locus." (PMID 20479942, 2010). "There is even stronger evidence in this subset for relationships between the STAT4 rs7574865 SNP and nephritis subphenotypes, and for an inverse relationship with oral ulcers." (PMID 18516230, 2008). "We believe that our data provide compelling evidence that STAT4 is associated with more severe SLE manifestations, particularly with nephritis and with the production of autoantibodies to double-stranded DNA." (PMID 18516230, 2008). "However, STAT4 has different roles in RA and SLE at least according to animal models: while in RA STAT4 deficiency in mice is protective, with inability of those mice to develop RA, in SLE STAT4-deficient mice have accelerated nephritis and higher mortality." (PMID 35844538, 2022). "To test this hypothesis we compared the genotype, allelic and haplotype frequencies from IRF5, STAT4 and TRAF1-C5 polymorphisms between IgAN patients and healthy controls, and SLE patients with and without nephritis, from TGFB1 polymorphisms between SLE patients and healthy controls." (PMID 20479942, 2010).
asthma (9 papers, 2011 to 2025). "It remains unclear whether the protective effect of mangiferin against asthma is associated with STAT4/6-signaling pathway." (PMID 24955743, 2014). "Conversely, genes such as FOXP3 and STAT4 exhibited stronger staining intensity in the control group, indicating distinct roles of these genes in the pathophysiological mechanisms of asthma." (PMID 40309741, 2025). "Furthermore, various studies have demonstrated that miR-21 is overexpressed in the airways of asthmatic subjects and that its expression is able to regulate the production of IL-12 through the modulation of the IL-12/STAT4 in asthma." (PMID 37892224, 2023). "Pathways exclusively enriched in AD included Cytokines and Inflammatory Responses, Th1/Th2 Differentiation, Dendritic Cell Pathway, Asthma, IL-12 STAT4 Signaling, CD40L Signaling, IL-4 Signaling, and CXCR3 Signaling, IL-2 STAT5 Signaling, CD8+ T-cell Signaling, and TCR Signaling." (PMID 28821884, 2017). "In addition, protein content and mRNA levels of STAT6 in asthma patients/models appeared to arise, STAT4 decreased abnormally." (PMID 24955743, 2014). "The STAT1 and STAT4 pathways are considered vital for Th1 differentiation, while the IL-4/IL-13/STAT-6 pathway has been confirmed to be the major modulator of Th2 differentiation in asthma pathophysiology." (PMID 34093516, 2021). "In addition, DClps produced more IL-10 and TGF-β than DCim, leading to dramatic decreases in the phosphorylation of both STAT4 and STAT6, which are critical in initiating Th1- and Th2-mediated immunoinflammatory processes in asthma, respectively." (PMID 32807859, 2020).
Behçet’s disease (8 papers, 2013 to 2025). "Polymorphisms in CD94/NKG2A, CD94/NKG2C, ERAP1, KLRC4, CCR1, and STAT4 were associated with Behçet's disease." (PMID 32010140, 2019). "In accordance, patients with inactive Behçet's disease had an impaired IL-12-induced STAT4 phosphorylation, associated with lower IFN-γ production." (PMID 32010140, 2019). "On the other hand, associations of these IL23R and STAT4 polymorphisms with systemic autoimmune diseases involving uveitis, such as Behçet’s disease, Vogt-Koyanagi-Harada disease or sarcoidosis, have been described in Asian populations but not in Europeans." (PMID 24312163, 2013). "Additionally, genetic factors may contribute to this regulation, as genetic variants in STAT3, STAT4, and JAK1 have been associated with an increased risk of ocular involvement in patients with Behçet’s disease." (PMID 40270958, 2025).
myocarditis (8 papers, 2012 to 2025). Myocarditis is a condition that is characterized by inflammation of the heart muscle (myocardium). "STAT4-deficient mice are resistant to induction of myocarditis by cardiac myosin immunization." (PMID 28407751, 2017). "In the present study, we observed significant upregulation of STAT4 in CVB3-induced acute myocarditis." (PMID 41222876, 2025). "Collectively, these findings demonstrate that STAT4 drives Spp1 expression in acute myocarditis, highlighting its potential as a therapeutic target for this condition." (PMID 41222876, 2025). "The overexpression of STAT4 results in increased focal necrosis, fibrosis, and interstitial hyperplasia, while the silencing of STAT4 and the NF-κB pathway represses the development of myocarditis." (PMID 37175422, 2023). "During myocarditis, signal transducer and activator of transcription 4 (STAT4) promotes the NF-κB pathway by increasing IKBα and p65 phosphorylation in myocardial cells." (PMID 37175422, 2023). "IL-12/STAT4 pathway of IFN-γ production protects against CVB3 replication during acute CVB3 myocarditis via elevating cardiac macrophage populations." (PMID 29868513, 2018). "Importantly, we identified STAT4 as a direct transcriptional regulator of OPN in macrophages during acute myocarditis, providing novel mechanistic insights into disease progression." (PMID 41222876, 2025). "However, the precise role of STAT4-mediated signaling in acute myocarditis remains incompletely understood." (PMID 41222876, 2025). "One limitation of our study is that, although we primarily focused on the STAT4-OPN axis, we included preliminary data showing a significant increase in Lipase G expression in acute myocarditis, which warrants further validation." (PMID 41222876, 2025). "Although IFNγ is increased in our model of CVB3 myocarditis in males, we showed that elevated IFN levels in male BALB/c mice with myocarditis are mediated by IL-18, which is downstream from TLR4, rather than traditional STAT4/IL-12 transcriptional activity." (PMID 39696682, 2024).
type 2 diabetes (8 papers, 2017 to 2023). "According to scientific research, STAT4 gene expression is associated with the risk of both type 1 and type 2 diabetes." (PMID 38275379, 2023). "In one such study, conducted among the Chinese Han population, it was reported that the STAT4 gene polymorphisms rs3821236, rs11893432, rs11889341, rs7574865, and rs897200 are associated with the risk of developing type 2 diabetes." (PMID 38275379, 2023). "Our results showed that only rs3821236 was associated with type 2 diabetes risk among the five candidate SNPs of STAT4 (rs3821236 A/G, rs11893432 G/C, rs11889341 T/C, rs7574865 T/G and rs897200 C/T)." (PMID 34176465, 2021). "STAT4 is activated by IL-12 and has been found to be associated with both type 1 and type 2 diabetes." (PMID 30044774, 2018). "Signal transducer and activator of transcription 4 (STAT4) has been associated with inflammation in both Type 1 and Type 2 diabetes and is primarily activated by IL-12 to promote cytotoxic responses and T helper 1 cell differentiation." (PMID 28107529, 2017). "Type II diabetes progression has also been linked to dysregulation of the IL12/STAT4 axis." (PMID 32973967, 2020). "Moreover, none of the co-dominant, dominant, recessive, or over-dominant models of the STAT4 rs10181656 polymorphism in the total study sample or in the male or female participants with type 2 diabetes showed an association with the risk of disease." (PMID 30044774, 2018). "STAT4 is primarily activated by IL-12, and has been implicated in both Type 1 and Type 2 diabetes." (PMID 28107529, 2017). "It is notable that several of the altered MAM proteins are associated with genes that have been discovered to play roles in both Type 1 and Type 2 diabetes (e.g., STAT4 and FOXO1)." (PMID 36139394, 2022). "In the present study, we provide the first evidence for the presence and role of STAT4 in skin wounds of a typical type 2 diabetic mouse model." (PMID 28107529, 2017). "More importantly, several studies have found Th1/Th2 cytokine imbalance in T2D patients, we speculate that STAT4 gene may play a potential role in the occurrence and development of type 2 diabetes." (PMID 34176465, 2021). "Our findings demonstrate that genetic variation of the transcription factor GATA3, not STAT4, is associated with the risk of type 2 diabetes in the Bangladeshi population." (PMID 30044774, 2018). "STAT4 also has a role in skin wounds, as demonstrated in a typical type 2 diabetic mouse model." (PMID 30044774, 2018). "Thus, the present study postulates that the genetic variation of the transcription factor GATA3, not STAT4, is associated with the risk of type 2 diabetes in the Bangladeshi population." (PMID 30044774, 2018).
colon carcinoma (7 papers, 2015 to 2024). "Slattery and co-authors, examining the JAK/STAT/SOCS signaling pathways in colorectal cancer, found that STAT4 rs10168266 CT + TT genotypes increased the risk of colon cancer under the dominant model (p < 0.001)." (PMID 39337665, 2024). "Among all the necroptosis signature genes, the oncogene signal transducer and activator of transcription 4 (STAT4) is a strong predictor of OS in colon cancer patients (p = 0.01688, HR = 2.9599, 95%CI: 1.2153–7.209)." (PMID 35874811, 2022). "STAT4 is critically involved in the metastasis of ovarian and colon cancers." (PMID 38294290, 2024). "Case-control studies, using more than 1550 patients with colon cancer and 750 cases of rectal cancer, demonstrated that JAK2, SOCS2, STAT1, STAT3, STAT5A, STAT5B, and STAT6 were associated with colon cancer, and that STAT3, STAT4, STAT6, and TYK2 were linked to rectal cancer." (PMID 36982677, 2023). "In particular, STAT3 was under-expressed while STAT4 and STAT5 were over-expressed in colon cancer tissue." (PMID 36968603, 2023).
COVID-19 (7 papers, 2020 to 2025). A disease caused by infection with severe acute respiratory syndrome coronavirus 2. "The gene STAT4 is the human transcriptomic factor of COVID-19." (PMID 36913345, 2023). "We then studied TFs potentially involved in the transcriptomic changes observed in COVID-19 monocytes, using Discriminant Regulon Expression Analysis (DoRothEA), and found that MAF family members, GATA3, STAT4, and IRF4, were associated with upregulated genes in severe COVID-19." (PMID 36443794, 2022). "Both distinct and common biological functions were identified as illustrated by inflammatory response genes being highly active in both COVID-19 and influenza, but genes for transcription factors, including inflammatory factors (i.e., NFKB1/2, and STAT4) were up-regulated in COVID-19." (PMID 32651212, 2020).